VEGFA (vascular endothelial growth factor A)
Diseases named in the same sentence as VEGFA in open-access papers (continued):
Sharing a sentence is not in itself a finding about the gene and the disease.
ovarian carcinoma (continued). "In addition, we found that circRhoC overexpression promotes VEGFA expression in ovarian cancer cells, and VEGFA expression level in ovarian cancer tissues was positively associated with circRhoC expression; moreover, through RIP assay, we suggest that circRhoC could directly bind with VEGFA protein." (PMID 31639291, 2019). "Assessing the VEGFA level in the blood of ovarian cancer and metastatic colorectal cancer patients is a simple and cost-effective way to monitor the effects of anti-angiogenic therapies during treatment." (PMID 31673071, 2019). "Western blotting confirmed that ovarian cancer cells transfected with a miR‐302e mimic expressed lower levels of VEGFA, TGF‐α and survivin protein." (PMID 31639291, 2019). "High VEGFA levels in blood correlate with advanced tumor stage and poor survival outcomes in ovarian cancer patients and the progression-free and overall survival of metastatic colorectal cancer patients." (PMID 31673071, 2019). "DANCR can increase vascular endothelial growth factor A (VEGF-A) expression, mediate vascular permeability as well as the multiplication and motion of endothelial cells and promote the neovascularization in ovarian cancer cell." (PMID 31799189, 2019). "Our data also suggested that miR-765 coordinates the formation of 3D channels-like structures through modulation of VEGFA/AKT1/SRC-α axis in SKOV3 ovarian cancer cells." (PMID 31157166, 2019). "Tumor angiogenesis was impaired by matrine treatment via regulating the expression of VEGFA of the ovarian cancer cells and ANG-1 of HUVECs co-cultured with A2780 and SKOV3 cells in vitro." (PMID 31601793, 2019). "Via DR2, dopamine obstructs the vascular permeability factor/vascular endothelial growth factor-A (VPF/VEGF) or norepinephrine mediated invasion of ovarian cancer cells." (PMID 28758939, 2017). "Analysis of among over 1,300 human ovarian cancers showed those with elevated VEGFA together with low miR‐128‐2 have the worst outcome, confirming the existence of an aggressive subset in which VEGFA is linked to miR‐128‐2 loss." (PMID 28179359, 2017). "Several studies reveal a connection between the HIF1A/VEGFA axis in drug resistance and poor prognosis in various cancer types including ovarian carcinoma." (PMID 27090655, 2016). "Furthermore, VEGFA supports stem cell activity in primary human ovarian cancer cultures and cell lines by activating VEGFR2-dependent Src signaling, thereby enhancing tumor sphere formation and increasing ALDH activity." (PMID 41373619, 2025). "These activated BM-MSCs subsequently increase secretion of interleukin-6 (IL-6), interleukin-8 (IL-8), and vascular endothelial growth factor A (VEGFA); promote angiogenesis in endothelial cells; and stimulate the migration of low-invasive ovarian cancer cells." (PMID 40806235, 2025). "Moreover, AKT1 and VEGFA can interact with each other, forming a positive feedback loop that further promotes ovarian cancer progression." (PMID 38666020, 2024). "Thus, targeting the AKT1 and VEGFA signaling pathways is a promising approach for treating ovarian cancer." (PMID 38666020, 2024). "But PARP-1 is overexpressed and may also stimulate angiogenesis in epithelial ovarian cancer cells by increasing the expression of VEGFA." (PMID 39624625, 2024). "Furthermore, several clinical trials are currently needed to investigate the efficacy of AKT1 and VEGFA inhibitors in the treatment of ovarian cancer." (PMID 38666020, 2024). "Abundant studies have confirmed that Treg enhances the establishment of VEGFA‐rich cancer microenvironment and promotes angiogenesis in ovarian cancer, which supports our hypothesis." (PMID 37434432, 2023). "The VEGFA-VEGFR2 Signaling pathway was enriched in the RUNX1 knockdown ovarian cancer cells." (PMID 38057816, 2023).
ovarian carcinoma (continued). "Of note, one study of ovarian cancer demonstrates that autophagy induced downstream of VEGFA promotes chemotherapy resistance, such that suppressing VEGFA expression inhibits autophagy biomarkers, increases apoptosis and decreases chemotherapeutic resistance overall." (PMID 34982945, 2022). "Additionally, SKOV3-cell-derived exosomal miR-205 governed proliferation, migration, invasion, and apoptosis via inhibition of vascular endothelial growth factor A (VEGFA) in ovarian cancer cells." (PMID 35024437, 2022). "Based on current bioinformatics analyses, VEGFA core target proteins may play a key role in preventing and treating ovarian cancer with COVID-19." (PMID 35464051, 2022). "Additionally, the activation of HIF1A and EPAS1 in cancer is connected with the vascularization processes, and ovarian carcinoma cells have been shown to express elevated VEGFA levels." (PMID 36230822, 2022). "Nevertheless, data regarding HIF1A, EPAS1, and VEGFA expression in ovarian cancer are scant." (PMID 36230822, 2022). "For example, the sole mAb licensed in the UK for the treatment of ovarian cancer is Bevacizumab (Avastin), which targets vascular endothelial growth factor A (VEGF-A), a molecule abundantly secreted by TAMs and fibroblasts to drive neo-angiogenesis and ascites formation." (PMID 35020853, 2022). "However, it has recently been shown in a ovarian cancer model that tumour-intrinsic STING promotes resistance to dual ICI therapy via vascular endothelial growth factor A (VEGF-A)." (PMID 34885119, 2021). "Therefore, the suppressive effect of GRB7 on VEGFA is consistent with GRB7 playing a role in regulating angiogenesis in ovarian cancer." (PMID 34783299, 2021). "High VEGFA is considered an indicator of poor prognosis in ovarian cancer." (PMID 33413202, 2021). "MiR-6086 suppressed ovarian cancer angiogenesis via regulating the OC2/VEGFA/EGFL6 axis." (PMID 34302635, 2021). "The levels of circASH2L were positively correlated with VEGFA expression in ovarian cancer samples." (PMID 33330483, 2020). "Several studies have shown that VEGFA is involved in the pathophysiology of ovarian cancer." (PMID 33330483, 2020). "We next assessed whether circASH2L affected the proliferation and invasion of ovarian cancer cells through a VEGFA-dependent mechanism." (PMID 33330483, 2020). "We observed an intricate association of the OC2/VEGFA/EGFL6 axis which could promote angiogenesis and tumorigenesis in ovarian cancer, together with other angiogenic factors." (PMID 32393810, 2020). "Taken together, our results reveal that miR-6086 can suppress the angiogenesis networks in ovarian cancer by down-regulating the OC2/VEGFA/EGFL6 axis, directly or indirectly, which may provide potential targets for tumor therapeutics." (PMID 32393810, 2020). "VEGFA stimulates cell mitogenesis and cell migration in ovarian cancer cells." (PMID 32481565, 2020). "Here, the expression of VEGFA was upregulated in ovarian cancer cell lines and tissues." (PMID 32393810, 2020). "Moreover, our functional analysis identified miR-6086 as a master regulator of tumorigenesis and angiogenesis in ovarian cancer by downregulating the OC2/VEGFA/EGFL6 axis." (PMID 32393810, 2020). "We describe a novel molecular mechanism by which RhoC forms a circRNA that not only sponges miR‐302e to positively regulate VEGFA, but may also directly bind and modulate VEGFA expression, which may promote tumorigenicity and progression in ovarian cancer." (PMID 31639291, 2019). "What’s more, exosomes from donor ovarian cancer cell SKOV3 shuttled miR-205 could advance the migration as wells as invasion of ovarian cancer cells via targeting VEGFA." (PMID 31719795, 2019). "Thus, more efforts are remained to further assess the function mechanisms of miR-205, its target gene VEGFA, and exosomes in the progression of ovarian cancer." (PMID 31719795, 2019).
ovarian carcinoma (continued). "The concomitant increased production of CXCL12, IL6, and VEGFA by CAFs within the tumor microenvironment could enable peritoneal metastasis of ovarian cancer via induction of the EMT program." (PMID 30380628, 2018). "VEGFRs were studied as targets of angiogenesis in ovarian carcinoma, resulting in approval of a monoclonal antibody against VEGFA, bevacizumab (Avastin), by The Food and Drug Administration in 2014; however, these agents were not directed at targeting the lymphogenous spread." (PMID 30445726, 2018). "The angiogenic factor, VEGFA, is a therapeutic target in ovarian cancer (OVCA)." (PMID 28179359, 2017). "Here, we show in both high‐grade serous OVCA lines and a primary clear cell OVCA culture that VEGFA drives ovarian cancer stem‐like cell expansion via Src‐dependent upregulation of DNMT3A, leading to methylation‐dependent loss of miR‐128‐2 and Bmi1 upregulation." (PMID 28179359, 2017). "Our results showed that EnSCs impaired the pro-angiogenetic ability of ovarian cancer cells in vivo through decreasing the expressions of VEGFA and HIF-1α in EOC cells, which might be mediated by EnSC-induced activation of FoxO3a in cancer cells." (PMID 27845405, 2016). "Moreover, ovarian cancer produced CC-chemokine ligand 28 under hypoxic conditions, resulting in Treg cell recruitment and the induction of tumor angiogenesis through VEGFA secretion." (PMID 25744203, 2015). "Our findings also highlight the therapeutic implications of targeting AKT1 and VEGFA pathways to mitigate cellular proliferation and growth, contributing valuable insights into the chemical constituents of indigenous Saudi plants and their synergistic mechanisms against ovarian cancer." (PMID 38666020, 2024). "CircRhoC might promote ovarian cancer development by upregulating miR-302e via targeting VEGFA." (PMID 37234708, 2023). "Moreover, an elevated level of VEGFA was found to be a key molecule in ovarian cancer." (PMID 36230822, 2022). "It would be interesting to test if the VEGFA mRNA levels and, especially, the expression of VEGFAb antiangiogenic spliced forms, could conversely be associated with the response to BEV as recently observed in colon cancer and proposed for ovarian cancer." (PMID 34680301, 2021). "In addition, our previous research reported that circRhoC functions not only as a miR-302e sponge to positively regulate VEGFA protein expression, but may also directly bind and modulate VEGFA expression to promote ovarian cancer development." (PMID 33483472, 2021). "We investigated whether circASH2L affected ovarian cancer by regulating VEGFA expression." (PMID 33330483, 2020). "We investigated whether circASH2L played a role in ovarian cancer by regulating VEGFA." (PMID 33330483, 2020). "The circRhoC/miR‐302e/VEGFA axis may provide a novel therapeutic target for ovarian cancer." (PMID 31639291, 2019). "Finally, VEGFA have been also related to ovarian cancer prognosis." (PMID 29855486, 2018). "Although this pro-angiogenic effect could be indirect, the depletion of Tregs in ovarian tumor-bearing-mice correlated with a strong reduction of the VEGFA at the tumor site, suggesting a relevant role of Tregs in promoting tumor angiogenesis in ovarian cancer." (PMID 25072019, 2014). "In other gynecological malignancies—ovarian cancer, we also observed differences in HIF1A and VEGFA expression levels in a case–control study, but also EPAS1 differed significantly." (PMID 39888575, 2026). "In ovarian cancer, factors including HGF, VEGFA, IGF, and stromal-derived BMPs drive CSC plasticity and contribute to relapse after platinum therapy." (PMID 41373619, 2025). "CCL2 released by omental adipocytes facilitates the migration and omental metastasis of ovarian cancer through the activation of PI3K/AKT/mTOR followed by an increase in HIF-1α and vascular endothelial growth factor A (VEGF-A)." (PMID 40076892, 2025).
ovarian carcinoma (continued). "VEGFA, PLAU, MMP2, MMP9, and MMP14 expression levels were reduced by stigmasterol treatment, which exerted a complex anticancer effect in the context of ovarian cancer." (PMID 35379271, 2022). "One of the most important regulators of angiogenesis is vascular endothelial growth factor A (VEGF-A), which is involved in the progression of the epithelial ovarian cancer." (PMID 35250573, 2022). "In particular, we found PI3K-Akt initiators; such as the RTKs EGFR1 and VEGFA, and the integrins ITGB3 and ITGB6, to be potential drug targets in ovarian cancer patients with high CTCFL expression." (PMID 35132075, 2022). "It has been shown that ovarian carcinoma cells presented higher VEGFA protein content, and HIF1A level was significantly correlated with VEGFA." (PMID 36230822, 2022). "More targeted therapies including vascular endothelial growth factor A (VEGF‐A) inhibitors and poly ADP-ribose polymerase (PARP) inhibitors have become new therapeutic options in managing ovarian cancer." (PMID 35646632, 2022). "In our study, we observed an increase in the expression of VEGFA and three cytokines (IL18, CCL7 and CXCL12) in fibroblasts after treatment with exosomes derived from ovarian cancer cells." (PMID 36012171, 2022). "MCP-1 specifically binds to CCR2 and activates PI3K/AKT/mTOR signaling pathway and its downstream factor hypoxia inducible factor-1α (HIF-1α) and vascular endothelial growth factor -A (VEGF-A), facilitating ovarian cancer cell metastasis to omentum." (PMID 34485124, 2021). "Oncoprint profile of CYCS, VEGFA, IL6, UQCRC1, UQCRFS1, COX5B, ACKR3/CXCR7, and FYN indicated that these genes were either amplified or overexpressed in 4–25% of the ovarian cancer patients." (PMID 34439877, 2021). "Ovarian cancer patients with EHD1 overexpression exhibit significantly worse responses to bevacizumab, which targets VEGFA." (PMID 31023336, 2019). "Of the 12 upregulated genes VEGFA, HJURP, CCNE2, and RAD51 were also upregulated in the tissue of ovarian cancer patients according to in silico microarray data (Oncomine)." (PMID 31319587, 2019). "Then we were wondering if changes in expression levels of miR-765, VEGFA, AKT1 and SRC-α have clinical implications in ovarian cancer." (PMID 31157166, 2019). "Further, a series of genes, such as cyclin E1 (CCNE1), cyclin B2 (CCNB2), cytochrome P450 family 3 subfamily A member 5 (CYP3A5), and vascular endothelial growth factor A (VEGFA), have been predicted as target genes for diagnosing ovarian cancer." (PMID 29482638, 2018). "Present work provides a novel rationale to support preclinical and clinical efforts to block VEGFA signaling at multiple levels, using inhibitors of VEGFR, Src and DNA methyltransferases to target ovarian cancer stem‐like cells." (PMID 28179359, 2017). "In ovarian carcinoma tissues, activation of STAT3 correlates with expression of VEGFA, VEGFR1 and VEGFR245." (PMID 28383032, 2017). "Filamin B (FLNB) suppresses the growth and metastasis of human ovarian cancer by down-regulating the activity of MMP-9 and secretion of vascular endothelial growth factor-A (VEGF-A)." (PMID 28538838, 2017). "Molecules such as VEGFA, MMP11 and TGF -β1 in particular CXCR2 play a very important role on cancer progression including ovarian cancer progression and hence their expressions with or without siRNA after anesthetic exposure were further determined." (PMID 27028996, 2016). "In ovarian cancer, hypoxia-induced angiogenesis, human, and mouse CD4+CD25+ Tregs secrete higher amounts of VEGFA (as compared to CD4+CD25− T cells) and promote EC proliferation in vitro and in vivo." (PMID 25072019, 2014). "Further validation with serums showed statistical significance in VEGFA and IGFBP7 levels among groups of patients with ovarian cancers, benign tumors, and control groups." (PMID 24349832, 2013).
ovarian carcinoma (continued). "Vascular endothelial growth factor A (VEGF-A) and its main signaling-receptor VEGFR2 (KDR) are expressed in primary ovarian tumors and autocrine VEGF-A/KDR loop protects ovarian carcinoma cells from anoikis." (PMID 22505926, 2012). "Similarly to the results shown in this study, the VEGFA expression was higher in cancer-affected tissue, whereas the HIF1A protein was at a lower level in malignant ovarian tumors." (PMID 39888575, 2026). "Subsequently, the survival and immune infiltration analysis demonstrated that the upregulation of five candidate genes, ITGB2, VEGFA, CLDN4, OCLN, and SPP1, were correlated with an unfavorable clinical outcome and increased immune cell infiltration in ovarian cancer." (PMID 36980477, 2023). "The CX3CR1_macro subpopulation may play a role in promoting tumor progression in ovarian cancer with high expression of BAG3, IL1B, and VEGFA." (PMID 35935940, 2022). "Moreover, for patients with ovarian cancer, VEGFA in serum is expected to replace CA125 and become a molecular marker for the early diagnosis of ovarian cancer." (PMID 36506508, 2022). "On the other hand, in ovarian cancer tissue samples, VEGFA was correlated neither with HIF1A nor EPAS1, but HIF1A was positively and moderately correlated with EPAS1 (R = 0.57, p < 0.0001)." (PMID 36230822, 2022). "The identification of CYCS, VEGFA, IL6, UQCRC1, UQCRFS1, COX5B, ACKR3/CXCR7, and FYN as pro-tumorigenic nodes designates them as the novel and potentially druggable targets for effective targeted adjuvant therapy for ovarian cancer." (PMID 34439877, 2021). "Similarly, treatment with fucoidan repressed the mRNA expression of angiogenesis related genes including VEGFA, VEGFB, VEGFC, VEGFD, FLT-1, FLT-4, and KDR in the ovarian cancer cells." (PMID 31936539, 2020). "QRT-PCR results of 50 patients showed that VEGFA mRNA expression was markedly higher in ovarian cancer samples than in paired non-tumor tissue." (PMID 33330483, 2020). "Several of these proteins have been described in the literature as mediators of ovarian cancer progression, including associations of their expression in tumor tissue or blood or ascites levels with ovarian cancer survival, for instance IL-6, GDF15, OPN/SST1, PVRL4, and VEGFA." (PMID 31737572, 2019). "Exosomes from donor ovarian cancer cell SKOV3, miR-205 and VEGFA could participate in the progression of ovarian cancer." (PMID 31719795, 2019). "We investigated the impact of tumor vascular endothelial growth factor A (VEGF-A) expression on the efficacy of LD paclitaxel chemotherapy and its interactions with the tyrosine kinase inhibitor SU5416 in the ID8 and ID8-Vegf models of ovarian cancer." (PMID 18182107, 2008). "PARPi agents have been approved to treat ovarian cancer patients with and without BRCA1/2 mutations and/or other HR deficiencies, and combined treatment with the PARPi olaparib and the VEGFA-selective blocker bevacizumab is FDA-approved for ovarian cancer as maintenance therapy." (PMID 38956205, 2024). "Network pharmacology analysis indicated that quercetin, luteolin, and baicalein may be important anticancer components in HD-SB, potentially acting on targets such as EGFR, MAPK1, VEGFA, and PIK3CG to inhibit ovarian cancer growth and migration via focal adhesion pathways." (PMID 39274982, 2024). "This study suggests that exosomes from donor ovarian cancer cell SKOV3 shuttled miR-205 could participate in the regulation of the proliferation, migration, invasion, apoptosis as well as EMT progression of receptor SKOV3 cells by targeting VEGFA." (PMID 31719795, 2019). "In conclusion, the oncogenic effect of RhoC in ovarian cancer is at least in part due to circRhoC, which functions not only as a miR‐302e sponge to positively regulate VEGFA protein expression, but may also directly bind and modulate VEGFA expression." (PMID 31639291, 2019).